SNORD113-6 (small nucleolar RNA, C/D box 113-6)
Synonyms: 14q(I-6)
Gene: Small nucleolar RNA gene on chromosome 14 (100,939,556 to 100,939,630, forward strand). Ensembl gene ENSG00000200215.
Gene Ontology:
Biological process: RNA processing
Cellular component: nucleolus
Homologues: Orthologues: chimpanzee SNORD113-6 (100% identical), macaque SNORD113-6 (97% identical), pig SNORD113-6 (91% identical), guinea pig SNORD113-6 (84% identical), mouse AF357425 (71% identical), mouse Gm55993 (71% identical). Paralogues in human: SNORD113-4 (89% identical), SNORD113-8 (81% identical), SNORD113-3 (80% identical), SNORD113-5 (76% identical), SNORD113-7 (75% identical), SNORD113-9 (73% identical), SNORD113-1 (67% identical), SNORD114-12 (65% identical), SNORD113-2 (63% identical), SNORD114-18 (63% identical), SNORD114-10 (61% identical), SNORD114-11 (61% identical), and 26 more.